PPARG (peroxisome proliferator activated receptor gamma)
Diseases named in the same sentence as PPARG in open-access papers (continued):
Sharing a sentence is not in itself a finding about the gene and the disease.
Obesity (continued). "However, as a gene that regulates fat synthesis, researchers usually achieve anti-obesity effects by inhibiting Dio2 and PPARγ." (PMID 31817377, 2019). "Among those, β3-adrenergic receptor agonist (such as isoproterenol) and the activators of Pparγ (such as rosiglitazone) have been widely used for treating obesity and type 2 diabetes through the browning-related modification in carbohydrate and lipid metabolism." (PMID 30641938, 2019). "Suppression of PPARγ by FABP4 in visceral fat may explain the reported role of FABP4 in the development of obesity-related morbidities, including insulin resistance, diabetes, and atherosclerosis." (PMID 30857223, 2019). "PPARγ belongs to the nuclear receptor superfamily, members of which are ligand-inducible transcription factors that modulate various pathways involved in the development of diabetes, obesity and AS." (PMID 31790366, 2019). "Whether PXR, LXR, and PPARγ interact during steatosis in lipid-related metabolite diseases such as obesity and diabetes remains to be determined." (PMID 31336903, 2019). "We showed that spilanthol significantly inhibits the adipogenic proteins C/EBPα, C/EBPβ, PPARα, PPARγ, and SREBP-1 in the liver, and that spilanthol has notable effects against obesity and associated metabolic abnormalities, such as insulin resistance and hyperlipidemia." (PMID 31052312, 2019). "Moreover, we found that obesity induced lipogenesis genes in db/db mice, as demonstrated by the increased transcription of genes such as PPARγ, SREBP-1c, ACOCA, FASN, and SCD." (PMID 31246177, 2019). "Reports have shown that H. sabdariffa derived bioactive compounds are potent in the treatment of obesity with an evident reduction in body weight, inhibition of lipid accumulation and suppression of adipogenesis through the PPARγ pathway and other transcriptional factors." (PMID 30626104, 2019). "PPARγ down-regulation could induce aggravation of adipocyte inflammation, in turn resulting in obesity-regulated disease." (PMID 31208033, 2019). "In conclusion, quercetin might prevent adipogenic differentiation but also induce the beiging of white adipocytes through the AMPK and PPARγ pathways to prevent obesity." (PMID 31346342, 2019). "Thus, it was concluded that PE has an anti-obesity effect by controlling lipid metabolism through PPARγ and UCP1." (PMID 31137922, 2019). "Several studies show that the oscillating gene came to vast changes of expression in diet-induced obesity and enhancing the rhythmical expression of PPARγ could be the key to regulating a series of reprogrammed transcriptions." (PMID 31336903, 2019). "Interestingly, T3s, including TRF and the purified isoforms, were reported to downregulate PPARγ in obesity studies but oppositely upregulate and activate PPARγ in diabetic models." (PMID 30845769, 2019). "Therefore, in obesity the increased expression of PU.1 in adipocytes modifies the adipocyte PPARg cistrome resulting in impaired glucose tolerance and insulin sensitivity." (PMID 31611602, 2019). "Therefore, in obesity the increased expression of PU.1 in adipocytes modifies the adipocyte PPARg cistrome." (PMID 31611602, 2019). "A germline mutation PPARG p.P12A was reported as a risk factor for obesity, noninsulin-dependent diabetes mellitus, and familial partial lipodystrophy was reported in a single study." (PMID 31346352, 2019). "Additionally, OTCs, as TBT, are considered obesogenic chemicals, which cause hyperplasia and hypertrophy of adipocytes and thus promote mammalian obesity via peroxisome proliferator-activated receptor gamma (PPARγ) signaling." (PMID 31178910, 2019). "Taken together, our results indicated that UHRF1 can promote proliferation of hADSCs and suppress adipogenesis thorough inhibiting PPARγ, and this study may provide a new insight for effective treatment of obesity and related metabolic diseases." (PMID 31428652, 2019).
Obesity (continued). "New studies suggest that exogenous activation of central PPARγ by its ligand TZD leads to weight gain which may contribute to obesity." (PMID 29997323, 2018). "For example, Japanese researchers reported that, in high-fat diets, mice lacking PPARγ exhibited significant dysplasia of adipocytes, smaller cell morphology, and lower fat content, causing pathological features such as obesity and severe insulin resistance." (PMID 30034368, 2018). "Because PGC-1α is an important regulator of PPARγ expression we asked whether in obesity the expression of PGC-1α would be reduced, and, if so, what would be the role of A20 in this context." (PMID 29678181, 2018). "PPARγ is an important member of the nuclear receptor super family of transcription factors, standing at the crossroads of controlling metabolic disorders, including obesity, insulin resistance, and cardiovascular diseases." (PMID 30463189, 2018). "Recent studies suggest that activation of PPARα and/or PPARγ contribute to weight gain and obesity." (PMID 29565812, 2018). "MiR-27b targets PPARγ, being reduced in obesity and increased after exercise." (PMID 30445764, 2018). "Furthermore, in states of obesity, the expression of PPARγ decreases with the consequent induction of a high grade of inflammation, angiogenesis, and fibrosis in the WAT and low levels of adiponectin, which limits the adipose tissue expansion." (PMID 30037087, 2018). "We provide evidence that VCE-004.8 is a selective partial PPARγ agonist lacking adipogenic activity that alleviates metabolic perturbations and inflammatory parameters associated to obesity." (PMID 30382123, 2018). "It would be interesting to establish whether the same signals are operative in tissues in which both hypoxia and PPARγ are present, like in adipose tissue in obesity." (PMID 29686697, 2018). "Nevertheless, our findings showed that CGA treatment activated PPARγ to a degree similar to RG treatment, potentially explaining the ability of CGA to increase insulin sensitivity and inhibit chronic inflammation caused by obesity." (PMID 30627576, 2018). "Regulation of PPARγ by miRNAs during adipogenesis and obesity." (PMID 30034368, 2018). "In mice, butyrate supplementation was shown to prevent insulin resistance and obesity, via a PPARγ-dependent switch from lipogenesis to fat oxidation, and to reduce high-fat diet-induced intestinal barrier dysfunction and metabolic alterations, including hepatic steatosis." (PMID 30591685, 2018). "Compared with PPARα and PPARγ, less is known about PPARβ/δ in relation to obesity and NAFLD." (PMID 29954129, 2018). "Therefore, specific regulation of the expression of the transcription factors C/EBPβ, C/EBPα, and PPARγ has become a target of obesity treatment." (PMID 30618744, 2018). "PPARγ is well known for its therapeutic potency of metabolic syndrome, type 2 diabetes and obesity." (PMID 30287730, 2018). "The results indicate that these compounds suppress C/EBPα and PPARγ expression and this action may explain the Ecklonia stolonifera Okamura effects on obesity." (PMID 30011911, 2018). "We provide evidence that the cannabidiol aminoquinone VCE-004.8 is a selective partial PPARγ agonist lacking adipogenic activity that alleviates metabolic perturbations and inflammatory parameters associated to obesity." (PMID 30382123, 2018). "The shortage of vitamin D and decreased level of PPARγ may be involved in obesity and cancer development." (PMID 29565812, 2018). "The present studies suggest that chlorogenic acid may also exert its anti-obesity potential through the inhibition of adipocyte Akt phosphorylation and of the downstream transcription factor PPARγ, a major regulator of adipogenesis." (PMID 28056918, 2017). "With respect to obesity development, the peroxisome proliferator-activated receptor γ (PPARγ) gene may play a critical role, functioning as the only gene that is both necessary and sufficient for fat cell production." (PMID 28122515, 2017).
Obesity (continued). "Importantly, while methylation affects PPARγ expression in animal and in vitro studies, only limited human data on PPARγ methylation, its relationship with obesity and/or with perinatal factors are available." (PMID 28122515, 2017). "As the main zinc efflux transporter at the cell membrane, and due to its opposite regulation than ZIP14 by obesity, we investigated if ZNT1 expression was associated with the same parameters as ZIP14, in terms of anthropometric markers, lipid profile, and PPARG levels." (PMID 28303117, 2017). "The mechanisms of anti-obesity effect of blended oil may be attributed to the regulation of PPARγ, C/EBPα, SREBP1, FAS and ATGL." (PMID 29089626, 2017). "However, latest research have found that the central activation of PPARγ or arachidonic acid contributes to obesity by direct regulation of indigestive behaviors or impairment of hypothalamic leptin signaling and hepatic energy homeostasis." (PMID 28806763, 2017). "Our results support an important association between rs1805192 and rs3856806 minor allele (G allele) of PPARG and increased T2DM risk, the interaction analysis shown a combined effect of G- obesity interaction between rs1805192 and obesity on increased T2DM risk." (PMID 28123453, 2017). "In the pathological process of obesity, insulin insufficient/resistance and diabetes, PPARG may be activated, and then promotes the accumulation of fatty tissue." (PMID 29254243, 2017). "Obesity has been reported to induce a decline in the activity and amount of PPARγ." (PMID 28878369, 2017). "A number of case-control studies demonstrated that obesity, insulin resistance/insufficient, metabolic syndrome and inflammation were correlative conditions in which PPARG could modify and regulate these actions, and influence the risk of cancer." (PMID 29254243, 2017). "In addition, PPARs (peroxisome-proliferator-activated receptors) are the nuclear hormone receptor including PPARα, PPARδ, and PPARγ, which play a critical role in regulation of obesity, cardiovascular diseases, and inflammation." (PMID 28293264, 2017). "HFD caused an overexpression of PPARγ in liver tissue with steatosis; thus, the deletion of PPARγ could protect against HFD-induced obesity and IR in mice." (PMID 28885549, 2017). "Other top key drivers like VEGFA, GAPDH and PPARG also play a role in breast cancer and obesity." (PMID 29156709, 2017). "Thus, a considerable amount of literature has emerged in the last ten years linking PPARG signalling with metabolic conditions such as obesity and diabetes, cardiovascular disease, and, more recently, cancer." (PMID 27579030, 2016). "We also propose that reduced PPARγ activity may explain the compromised BAT activities in obesity and metabolic syndrome." (PMID 28042289, 2016). "Since PPARγ plays an important role in adipogenic differentiation and is a receptor for insulin sensitizing drugs, regulation of its expression is of importance with respect to nutrition, obesity and diabetes." (PMID 26797605, 2016). "Expression of PPARγ is increased in fatty livers of several animal models of obesity and diabetes." (PMID 27348013, 2016). "Mice lacking PPARγ in fat, muscle, or liver are predisposed to develop insulin resistance while mice with increased PPARγ activities are protected from obesity-associated insulin resistance." (PMID 27069498, 2016). "The identification of both the possible targets that regulate PPARγ, as well as the active components that modulate PPARγ are two key steps towards fighting obesity via the inhibition of adipogenesis, and the continuation of these elucidation efforts is imperative." (PMID 27669202, 2016). "The activation of PPARγ might have advantageous effects on the link between the stromal macrophage and visceral adipocytes, altered during in obesity." (PMID 27347932, 2016).
Obesity (continued). "While the understanding and discovery of new pathways for PPARγ regulation are proceeding, additional therapeutic targets for obesity treatment are presented, and the further application of possible active natural products could be conducted." (PMID 27669202, 2016). "We found no previous studies examining interaction between PPARG rs1801282 and dietary fish, but studies have previously shown that this variant interacts with fat intake in relation to obesity among non-pregnant woman and men." (PMID 26930408, 2016). "MiR-122 decrease was described central in hepatic fatty-acid and cholesterol synthesis rate, by reducing hepatosteatosis, together with miR-223 in obesity, also with miR-425, miR-126, miR-16, miR-634, miR-519d, miR-27 and miR-519d for target PPARγ, miR-26 triglyceride accumulation." (PMID 27147943, 2016). "Additionally, PPARγ is elevated in FLs from murine model of diabetes and obesity and is critical for the development of hepatic steatosis." (PMID 26770990, 2016). "Therefore, by targeting the hepatic PPARγ pathway, the alternating diet also exerts its protective function against obesity-induced hepatic steatosis." (PMID 27189661, 2016). "Results suggested that CPE and CFSE administration could ameliorate obesity and metabolic disorders in HF diet-induced obesity mice probably through the inhibition of PPARγ and LXRs gene expressions." (PMID 26907240, 2016). "Some flavonoids selectively modulate PPARγ activity and suppress adipogenesis or obesity." (PMID 28042289, 2016). "The discovery of PPARγ’s antagonistic activity of CAB may imply the potential of thiophene-acetylene as an anti-obesity treatment." (PMID 27669202, 2016). "The Pro115Gln polymorphism, a very rare gain-of-function mutation in PPARγ, is associated with obesity but not IR." (PMID 28042289, 2016). "Thus, in this review, we discuss the effects of flavonoids on PPARγ-mediated obesity based on the role of PPARγ as a master regulator of adipogenesis." (PMID 28042289, 2016). "In vitro, Peroxisome Proliferator-Activated Receptor gamma (PPAR-γ), a regulator of adipocyte differentiation implicated in obesity, is strongly upregulated following demyelination mediated by antibodies directed against the Myelin Oligodendrocyte Glycoprotein (MOG) in the presence of complement." (PMID 27721574, 2016). "Our results suggest that dietary supplement of isorhamnetin may be beneficial to prevent obesity and steatosis and PPARγ antagonists may be useful to treat hepatic steatosis." (PMID 26775807, 2016). "Previous studies provided evidence that the NCOA3 gene (NCOA3) plays a primary role in adipogenesis as well as obesity by regulating the gene expression of peroxisome proliferator-activated receptor γ (PPARγ) - the master regulator of adipocyte development and differentiation." (PMID 26449542, 2015). "Chemicals that specifically activate PPARγ and up-regulate expression may promote the development of obesity." (PMID 25314719, 2015). "As epigenetic alterations in AT may be associated with obesity-related phenotypes, we performed quantitative analysis of single CpG methylation within the LPL, ADIPOQ and PPARγ promoters." (PMID 26148147, 2015). "PPARγ (peroxisome proliferator-activated receptor gamma) is the master regulator of adipocyte development, and activation of PPARγ can lead to adipogenesis and obesity." (PMID 25738596, 2015). "Furthermore, some dysregulated genes associated with obesity were correctly regulated by chelerythrine, including adiponectin and adipsin, which are dysregulated downstream of CDK5-mediated PPARγ phosphorylation." (PMID 26183621, 2015). "It is known that PPARγ is elevated in murine models of diabetes and obesity." (PMID 25875942, 2015). "Alternatively, in parallel with accumulation of VAT-resident Foxp3+ Treg cells, augmentation of such suppressive activities of PPARγ-expressing Treg cells achieved by ligand activation may enable better control of inflammation in obesity." (PMID 26339623, 2015).
Obesity (continued). "Moreover, drugs that target PPARγ have been shown to possess anti-inflammatory effects in animal models of obesity." (PMID 25709707, 2015). "Thus, a greater understanding of PPARγ expression and regulation is critical for understanding obesity and metabolic syndrome (MS)." (PMID 25128964, 2014). "Furthermore, the pharmacological activation of PPARγ was found to induce ADIPOQ expression to regulate glucose metabolism in obesity." (PMID 25093444, 2014). "Dietary fat restriction is a current strategy to tackle obesity and, telmisartan, as a renoprotective agent, may mediate cholesterol efflux by activating PPARγ." (PMID 24468233, 2014). "Combination therapy of MTP inhibitor and PPARγ agonist might be more useful in the treatment of type 2 diabetes accompanied with obesity and insulin resistance." (PMID 24772450, 2014). "Investigating the molecular mechanisms that control PPARγ expression during adipogenesis is critical for understanding the development of white and brown adipose tissues, as well as pathological conditions such as obesity and diabetes." (PMID 24904744, 2014). "For example, Twist 1 might influence the physiological and pathological processes related to PPARγ during the development of obesity." (PMID 25128964, 2014). "Among the studied natural products, amorfrutin 1 is the only one that was investigated so far for interference with PPARγ Ser273 phosphorylation and was found to suppress phosphorylation at this residue in the visceral white adipose tissue of diet-induced obesity (DIO) mice." (PMID 25083916, 2014). "For instance, the Pro12Ala polymorphism (rs1805192) in PPARG has been found associated with obesity in non-diabetic men." (PMID 25089907, 2014). "Studies on the transcription factors that control PPARγ expression in adipose progenitors may provide insight into adipocyte maturation in normal and obesity states." (PMID 25128964, 2014). "For example, it is not clear whether Twist 1 directly regulates PPARγ expression or how PPARγ acts as a molecular bridge among the Twist 1-related processes in obesity." (PMID 25128964, 2014). "In regard of IUGR and obesity PPARγ expression was found to be increased in human placenta; hereby this upregulation could be interpreted as adaptive response to the IUGR placenta preventing insufficient nutrient supply." (PMID 23554810, 2013). "Furthermore, ERK1/2 can target and activate several nuclear receptors, e.g., estrogen receptor (ER), a receptor upregulated in breast cancer, or peroxisome proliferator-activated receptor gamma (PPARγ), a receptor involved in diabetes and obesity." (PMID 23455463, 2013). "Although PPARγ agonists such as rosiglitazone and pioglitasone improve insulin resistance and glucose tolerance in obese mice models, previous studies also have shown that inhibition of PPARγ signaling significantly improve metabolic disorders including obesity, dyslipidemia, and diabetes." (PMID 23533476, 2013). "In the present study, we showed that rosiglitazone, a PPARγ agonist, could reduce obesity-induced systemic inflammation, insulin resistance, macrophage accumulation and atherosclerotic plaque formation." (PMID 23620818, 2013). "aP2-diphtheria toxin transgenic mice and PPARγ (peroxisome proliferator activated receptor gamma) hypomorphic mice lack the massive adipose stores that are characteristic of obesity, although they still develop the clinical correlates of hyperlipidemia and fatty liver." (PMID 24192824, 2013). "In this study, we simultaneously confirmed that the anti-obesity abilities of DOW-RMD in inhibiting PPARγ and C/EBPα expression in differentiation and lipoprotein lipase activity in lipogenesis were contributed to by the DOW-increased monascin and ankaflavin levels and the ions of DOW, respectively." (PMID 24132179, 2013).